GOLGA8B (golgin A8 family member B)
Description:
May be involved in maintaining Golgi structure.
Synonyms: GOLGA5
Tractability: Antibody: UniProt places it where antibodies can reach, with high confidence. PROTAC: ubiquitination databases record sites on it.
Gene: Protein-coding gene on chromosome 15 (34,525,095 to 34,588,503, reverse strand). Ensembl gene ENSG00000215252.
Subcellular location: Golgi apparatus, Golgi stack membrane
Subcellular location (Human Protein Atlas): Golgi apparatus; Cytosol
Gene Ontology:
Biological process: Golgi organization
Cellular component: cis-Golgi network; Golgi cis cisterna; Golgi cisterna membrane; Golgi apparatus
Genetic constraint (gnomAD): Loss-of-function variants: 1 observed, 3.76 expected, observed/expected ratio (o/e) 0.27, 90% interval 0.093 to 1.23. That is too few expected variants to judge how well the gene tolerates losing a copy. Missense variants: 10 observed, 37.13 expected, observed/expected ratio (o/e) 0.27, 90% interval 0.17 to 0.46. Synonymous variants: 7 observed, 12.89 expected, observed/expected ratio (o/e) 0.54, 90% interval 0.31 to 1.02.
Homologues: Orthologues: mouse Golga2 (43% identical), dog GOLGA2 (42% identical), tropical clawed frog golga2 (32% identical), zebrafish golga2 (30% identical), Drosophila melanogaster GM130 (22% identical), Caenorhabditis elegans golg-2 (18% identical), rat Golga2l1 (5% identical). Paralogues in human: GOLGA8A (99% identical), GOLGA8F (76% identical), GOLGA8G (76% identical), GOLGA8S (73% identical), GOLGA8M (70% identical), GOLGA8H (69% identical), GOLGA8J (69% identical), GOLGA8N (69% identical), GOLGA8O (69% identical), GOLGA8Q (69% identical), GOLGA8T (69% identical), GOLGA8K (69% identical), and 6 more.
Diseases named in the same sentence as GOLGA8B in open-access papers:
GOLGA8B is named in the same sentence as 12 diseases in open-access papers, as found by Europe PMC text mining. Sharing a sentence is not in itself a finding about the gene and the disease. The quoted sentences say what the papers report.
adenoma (3 papers, 2018 to 2025). A neoplasm arising from the epithelium. "APC is the gene most frequently mutated in conventional colon adenomas; four genes recurrently mutated in adenomas CTNNB1 (catenin-β1), KRTAP4-5 (keratin-associated protein 4–5), GOLGA8B (golgin A8 family member B) and TMPRSS13 (transmembrane protease, serine 13) had the oncogene pattern." (PMID 29652830, 2018). "Lin and colleagues characterized the mutational alterations using WES and proposed four genes (CTNNB1, KRTAP4-5, GOLGA8B, and TMPRSS13) as the potential somatic drivers in conventional adenomas." (PMID 40757636, 2025).
clear cell renal cell carcinoma (2 papers, 2020 to 2024). "Furthermore, certain long non-coding RNAs play a role in the development of clear cell renal cell carcinoma by regulating GOLGA8B expression levels." (PMID 38730195, 2024).
dementia (2 papers, 2024). Loss of intellectual abilities interfering with an individual's social and occupational functions. "GOLGA8B is associated with various diseases, and alterations in GOLGA8B expression may contribute to the development of conditions such as dementia and coronary atherosclerosis." (PMID 38730195, 2024).
lung squamous cell carcinoma (2 papers, 2022 to 2024). "For instance, one study revealed that GOLGA8B can promote lung squamous cell carcinoma by suppressing the expression of STAT3." (PMID 38730195, 2024). "GOLGA8B knockdown inhibits cell invasion by suppressing the STAT3 signaling pathway in lung squamous cell carcinoma." (PMID 36289596, 2022).
prostate carcinoma (2 papers, 2022 to 2024). A carcinoma that arises from epithelial cells of the prostate gland. "GOLGA8B may be utilized as a predictive marker for prostate cancer based on its expression level." (PMID 36289596, 2022).
lung carcinoma (1 paper, 2022). "The GOLGA8B/miR-30d-5p/RUNX2 regulatory axis has important functions in lung cancer cell proliferation and stemness via regulatory and physical interactions of GOLGA8B and RUNX2 with both stemness-related genes and stemness TFs." (PMID 36289596, 2022).
myositis (1 paper, 2018). "PI4KAP1 was found to have a higher expression in CD4+ T cells of HLA-DRB1*03-positive patients with myositis, and TRGC2, CTSW, HPCAL4, ZNF683, and GOLGA8B were found to have a higher expression in CD4+ T cells of HLA-DRB1*03-negative patients with myositis." (PMID 30157932, 2018). "We found that PI4KAP1 had a higher expression in CD4+ T cells of HLA-DRB1*03-positive myositis and that TRGC2, CTSW, HPCAL4, ZNF683, and GOLGA8B had a higher expression in CD4+ T cells of HLA-DRB1*03-negative myositis patients." (PMID 30157932, 2018).
tumor (3 papers, 2020 to 2024). "In this study, we collected normal para-cancer and tumor tissues to assess GOLGA8B expression at both the mRNA and protein levels." (PMID 38730195, 2024). "Eventually, HNRNPA2B1, GOLGA8B and MAPK8IP3 were picked out to be significantly associated with tumour prognosis." (PMID 32485038, 2020). "Our study found that HNRNPA2B1, GOLGA8B and MAPK8IP3 were identified to be tightly associated with tumour progression and prognosis, and further researches are needed before clinical application." (PMID 32485038, 2020). "Additionally, HNRNPA2B1, GOLGA8B and MAPK8IP3 were identified to be tightly associated with tumour progression and prognosis." (PMID 32485038, 2020). "The association between GOLGA8B and tumour progression or prognosis has not been explored deeply." (PMID 32485038, 2020).
GOLGA8B also shares sentences with these, for which no sentence is quoted: Alzheimer disease (1 paper); cancer (1); colon adenoma (1); coronary atherosclerosis (1).